PVT1 (Pvt1 oncogene)
Diseases named in the same sentence as PVT1 in open-access papers (continued):
Sharing a sentence is not in itself a finding about the gene and the disease.
prostate carcinoma (continued). "PVT1 can accelerate the intrusion and transfer by prostate carcinoma via regulating EMT." (PMID 31572428, 2019). "We detected PCA3, PVT1, and GAS5 lincRNAs as differentially expressed genes in the patient cancer samples compared with adjacent non-tumor tissues; these lincRNAs have been recently shown to be associated with prostate cancer." (PMID 29875794, 2018). "PVT1 regulated prostate cancer cell viability and apoptosis depending on miR‐146a." (PMID 27794184, 2016). "Furthermore, miR‐146a overexpression eliminated the inhibition effect of PVT1 knockdown on cell proliferation and apoptosis in prostate cancer cells." (PMID 27794184, 2016). "miR‐146a overexpression eliminated the effects of PVT1 knockdown on prostate cancer cells." (PMID 27794184, 2016). "Additionally, the effect of neighboring genes highlights the complexity of PVT1 in prostate cancer." (PMID 32117705, 2020). "Evidence has accumulated that PVT1 could be used as potential biomarker for prostate cancer." (PMID 31877167, 2019). "Moreover, rs378854 can also interact with MYC or PVT1 promoter in prostate cancer." (PMID 31309249, 2019). "However, the target gene of PVT1 and the molecular mechanism of modulating the prostate cancer tumorigenesis were still unknown." (PMID 27794184, 2016). "It implied that there may be a certain relationship between PVT1 and miR‐146a in prostate cancer." (PMID 27794184, 2016). "Therefore, we suggest that differential binding of YY1 to the prostate-cancer associated variant rs378854 might be functionally important for the regulation of MYC and/or PVT1 expression." (PMID 21814516, 2011). "A number of well-known oncogenic lncRNAs in other cancers such as DANCR, MALAT1, CCAT1, PVT1, TUG1 and NEAT1 have also been shown to act as oncogenes in prostate cancer." (PMID 37025585, 2023). "The same mechanism was shown to be at play in the tumorigenic prostate cancer cell line (MDA PCa 2b), which significantly reduced its PCNA expression when PVT1 exon 9 expression was silenced." (PMID 33796469, 2021). "Recent studies propose that several lncRNAs including LOXL1-AS1, PVT1, and HOTAIR exhibit abnormal expression in prostate cancer." (PMID 32440687, 2020). "Together, these chromatin-conformation data suggest that the rs72725854-harboring enhancer forms a spatial network with PCAT1, PRNCR1, PVT1, and MYC genes in 3D nuclear space in prostate cancer cells." (PMID 32680982, 2020). "To further investigate the relationship between PVT1 and miR‐146a, we evaluated the expression of miR‐146a in three prostate cancer cell lines (LNCaP, PC‐3 and DU145) transfected with either PCDNA3‐PVT1 or si‐PVT1." (PMID 27794184, 2016). "To explore the mechanism of negative regulation of miR‐146a by PVT1, we analyzed the level of three active DNA methyltransferases (DNMT1, DNMT3a, and DNMT3b) in prostate cancer cell lines using qRT‐PCR when PVT1 was aberrantly expressed." (PMID 27794184, 2016). "We suggest that increased levels of PVT1 in advanced prostate cancer tumors could modulate an enhanced epigenetic inhibitory effect of AR on NOV/CCN3 expression, through the AR-EZH2-PVT1 axis." (PMID 33430890, 2021). "The possible involvement of PVT1 in mediating androgen-induced gene expression downregulation in prostate cancer has not been explored." (PMID 33430890, 2021). "PVT1 has been reported to sponge miR-186; to downregulate E-cadherin but upregulate vimentin, snail and Twist1; and to induce EMT and promote the progression of prostate cancer." (PMID 31497532, 2019). "The non-protein coding gene locus plasmacytoma variant translocation 1 (PVT1) is located at 8q24 and is dysregulated in prostate cancer." (PMID 31877167, 2019). "In addition, PVT1 overexpression obviously increased the activity of DNA methyltransferases (DNMT1, DNMT3a, and DNMT3b) in prostate cancer cells." (PMID 27794184, 2016).
prostate carcinoma (continued). "In this study, we apply support vector classifiers to develop a composite score for detecting PCa using expression levels of PVT1 exons 4A, 4B, and 9 derived from a non-tumorigenic prostate epithelial cell from a Caucasian male and a tumorigenic prostate cancer cell line derived from a moAA." (PMID 33796469, 2021).
cervical carcinoma (56 papers, 2016 to 2025). A carcinoma arising from either the exocervical squamous epithelium or the endocervical glandular epithelium. "Plasmacytoma variant translocation-1 (PVT1) promotes the proliferation and metastasis of cervical cancer." (PMID 35103065, 2022). "Increased PVT1 expression in cervical cancer contributes to cancer phenotype and associates with poor prognosis." (PMID 33777808, 2021). "The PVT1 oncogene, a long non-coding RNA gene, has been associated with multiple cancers including cervical cancer." (PMID 34175494, 2021). "One of the hypoxia-induced lncRNAs, PVT1 (plasmacytoma variant translocation 1), was implicated in cervical cancer progression, likely through its interaction with a multifunctional shuttling protein, nucleolin." (PMID 32370770, 2020). "Future work is necessary to elucidate the biological function of the PVT1-Myc association in cervical cancer." (PMID 27232880, 2016). "Collectively, the cell phenotypic (loss of PVT1) functional data suggests that PVT1 is required for proliferation, maintenance and cisplatin resistance of cervical cancer cells." (PMID 27232880, 2016). "Functionally, PVT1 knockdown in cervical cancer cells was associated with decreased proliferation, migration and invasion and increased apoptosis and cisplatin sensitivity, suggesting that this lncRNA likely plays a pivotal and multifaceted role in cervical carcinogenesis." (PMID 27232880, 2016). "Thus, while the current manuscript indicates that PVT1 plays a pivotal role in cervical carcinogenesis, future experiments are required to definitively pinpoint the precise splice variant(s) responsible for the oncogenic effects of PVT1 in cervical cancer." (PMID 27232880, 2016). "In vitro, PVT1 expression is significantly augmented by cancer-related hypoxic and immune-stimulatory treatments, suggesting possible mechanisms underlying its heightened expression in cervical cancer." (PMID 27232880, 2016). "Finally, the effects of PVT1 on cervical cancer cells may be facilitated by its association with the protein Nucleolin." (PMID 27232880, 2016). "Thus, our future research aims to examine the importance of the PVT1-Nucleolin interaction in the context of these processes, and whether they underlie the oncogenic effects of PVT1 in cervical cancer in vivo." (PMID 27232880, 2016). "Another study also showed that upregulation of PVT1 mitigates proliferation and invasion of cervical cancer cells." (PMID 39912983, 2025). "Hi‐C and 4C‐seq analyses in cervical cancer cell line (HeLa) demonstrated chromatin looping interactions between integrated HPV and MYC/PVT1 regions (~ 500 kb apart), leading to allele‐specific overexpression." (PMID 38013620, 2024). "Evidence in the literature also indicates that PVT1 promotes cervical cancer progression by silencing MIR200B through EZH2 interaction, leading to histone H3K27 trimethylation and MIR200B inhibition." (PMID 39372928, 2024). "Reducing the expression of PVT1 can increase the apoptosis and cisplatin sensitivity of cervical cancer cells." (PMID 36869031, 2023). "For example, PVT1 is upregulated in cervical cancer and promotes the proliferation, migration, and invasion of cervical cancer cells." (PMID 36869031, 2023). "This suggests that PVT1 promotes paclitaxel resistance in cervical cancer cells, promoting EMT transformation." (PMID 36890809, 2023). "After deeper investigation, researchers have also revealed that lncRNA PVT1 is upregulated in various malignancies, such as cervical cancer, clear cell renal cell carcinoma, and thyroid cancer, and acts as an oncogene." (PMID 35038974, 2022). "The expression of PVT1 is upregulated in cervical cancer cells, and PVT1 binds directly to miR-140-5p, which promotes the expression of Smad3 and then promotes the development of cervical cancer." (PMID 35103065, 2022).
cervical carcinoma (continued). "The plasmacytoma variant translocation 1 gene (PVT1) and GIHCG have been reported to bind to EZH2 and recruit it to the mir-200b~429 cluster promoter in cervical cancer (CC) and HCC." (PMID 33809566, 2021). "The PVT1 gene is located in the chromosomal locus 8q24.21, which is one of the regions previously reported to contain integration sites in cervical carcinomas more often than other loci." (PMID 34175494, 2021). "Circ_PVT1 was upregulated in cervical cancer, while silencing of circ_PVT1 prevented cervical cancer cells’ progression via targeting epithelial-mesenchymal transition pathway." (PMID 34336825, 2021). "By reducing the level of miR-200b and miR-195, PVT1 promotes progression and chemoresistance in cervical cancer." (PMID 31497532, 2019). "Previous studies also confirmed that PVT1 is upregulated in cervical cancer and promote the progression of disease." (PMID 29760583, 2018). "Then we carried out a meta-analysis on the relationship between the expressions of HOTAIR/PVT1 and the OS of patients with cervical cancer." (PMID 28977961, 2017). "On the other hand, miR-152 and miR-200b have been reported to be regulated by PVT1 in hepatic stellate cells and cervical cancer cells, respectively." (PMID 28404954, 2017). "In cervical cancer, PVT1 expression is shown to be upregulated in response to hypoxia and immune response stimulation." (PMID 28789687, 2017). "In cervical cancer, hypoxia-inducible lncRNA PVT1 (plasmacytoma variant translocation 1) was suggested to exert its oncogenic role through association with the multifunctional protein, Nucleolin." (PMID 28789687, 2017). "Our results revealed that PVT1 is increased in the cervical cancer patients, and the high expression of PVT1 was related with the poor prognostic outcome of cancer patients." (PMID 28977961, 2017). "PVT1 expression was also examined in vitro, with the SiHa cervical cancer cell line expressing the highest levels of the lncRNA compared to others." (PMID 27232880, 2016). "Here, we show that PVT1 expression is significantly higher in cervical cancer tissue compared to normal controls." (PMID 27232880, 2016). "Ensembl data suggests the presence of at least 25 unique human PVT1 transcripts and exon 2 of PVT1 can also form a circular RNA (circRNA) that is highly expressed in HeLa cervical cancer cells, thus making the study of PVT1 function particularly challenging." (PMID 27232880, 2016). "Using Kaplan-Meier survival analysis and log-rank tests, we found that high PVT1 expression was significantly correlated with shorter cumulative survival time for cervical cancer patients (p = 0.03)." (PMID 27232880, 2016). "To begin our in vitro examination into the role of PVT1 in cervical cancer cells, we determined PVT1 expression levels in various commercially available cervix-derived cell lines via qPCR." (PMID 27232880, 2016). "Collectively, our results provide strong evidence for an oncogenic role of PVT1 in cervical cancer and lend insight into potential mechanisms by which PVT1 overexpression helps drive cervical carcinogenesis." (PMID 27232880, 2016). "PVT1 and local miRNA expression levels were determined by qPCR for cancerous and adjacent normal tissues from cervical cancer patients." (PMID 27232880, 2016). "Next, SiHa cells transfected with PVT1-targeted siRNA (siPVT1) were utilized to examine the effects of this lncRNA on cervical cancer cell proliferation and motility." (PMID 27232880, 2016). "Functional assays were carried out using both siRNA and LNA-mediated knockdown to examine PVT1’s effects on cervical cancer cell proliferation, migration and invasion, apoptosis, and cisplatin resistance." (PMID 27232880, 2016). "Work is ongoing to elucidate the mechanistic properties of the PVT1-Nucleolin interaction in cervical cancer cells." (PMID 27232880, 2016).
cervical carcinoma (continued). "The 127 cervical cancer patients were divided into high and low PVT1-expressing groups, using the median PVT1 expression level, to investigate their correlation with prognosis." (PMID 27232880, 2016). "In cervical cancer cell lines, PVT1 knockdown resulted in significantly decreased cell proliferation, migration and invasion, while apoptosis and cisplatin cytotoxicity were significantly increased in these cells." (PMID 27232880, 2016). "PVT1 expression was significantly higher in tumors from cervical cancer patients versus adjacent normal tissue (n = 127 tumor; n = 30 adjacent normal; p<0.001)." (PMID 27232880, 2016). "To this end, using RNA affinity chromatography in conjunction with mass spectrometry sequencing, we identified potential protein binding partners of PVT1 in vitro using whole-cell lysates from SiHa cervical cancer cells." (PMID 27232880, 2016). "Together, these data suggest that, in general, PVT1 expression is elevated in cervical cancer tumors and that the higher the expression of PVT1, the poorer the prognosis." (PMID 27232880, 2016). "In summary, we propose that high expression levels of PVT1 contribute to the cervical cancer phenotype via modulation of cell proliferation, apoptosis, and cell motility." (PMID 27232880, 2016). "Of note, these effects of PVT1 knockdown are mimicked in another cervical cancer cell line, HeLa, providing further support for a role of this lncRNA in cervical carcinogenesis." (PMID 27232880, 2016). "Interestingly, PVT1, one of lncRNA, was influenced by ALKBH5 silencing and associated with MMP2/9 expression in cervical cancer cells." (PMID 37639643, 2023). "In CC, lncRNA PVT1 regulated miR-195 to enhance the paclitaxel resistance in cervical cancer." (PMID 36793374, 2023). "PVT1 has been discovered as a ceRNA to promote progression of cervical cancer by sponging niR-424." (PMID 34991683, 2022). "Some previous studies have revealed the different gene expression patterns of HPV-negative and HPV-positive subtypes of cervical cancers, such as Oct4, the long noncoding RNA (lncRNA) PVT1, and lncRNA SRA1,9, 10, 11 implying that various molecular pathways are involved." (PMID 33997099, 2021). "Furthermore, PVT1 has shown to decrease miR-195 and miR-200b expression in cervical cancer either by enhancing histone H3K27me3 in the miR-195 and miR-200b promoters or by direct binding of miR-195 and miR-200b." (PMID 32154165, 2020). "It hasbeen elucidated that serum levels of PVT1 are increased ingastric cancer, small cell lung cancer, and cervical cancer,all of which are accompanied by low overall survival rates.ehTrefore, lncRNA PVT1 can be considered a diagnosticmarker and a suitable therapeutic target." (PMID 30930624, 2018). "Next, we sought to identify specific oncogenic stressors that may drive enhanced PVT1 expression in cervical cancer." (PMID 27232880, 2016). "Finally, we have identified Nucleolin as a protein binding partner of PVT1 in cervical cancer cells." (PMID 27232880, 2016). "Perhaps most importantly, high PVT1 expression correlates with poorer survival outcome in cervical cancer patients and may play a central role in resistance of cervical cancer cells to cisplatin." (PMID 27232880, 2016). "Thus, it appears that PVT1 likely exerts its effects through an alternative mechanism in cervical cancer cells." (PMID 27232880, 2016). "Thus, the present study was designed to investigate the role of PVT1 in cervical cancer in vitro and in vivo." (PMID 27232880, 2016). "Thus, our next experiments were designed to investigate the role of PVT1 in apoptosis and cisplatin sensitivity in cervical cancer cells." (PMID 27232880, 2016). "They found increased expression of four LncRNAs—HOTAIR, PVT1, XLOC‐000303, and AL592284.1—in cervical cancer compared to healthy samples, suggesting their potential as biomarkers for cancer prediction." (PMID 40953835, 2025).
cervical carcinoma (continued). "A recent study observed significantly higher expression of the lncRNA PVT1 in patients with HPV-positive cervical cancer and patients with HPV-negative cervical cancer than in the control group." (PMID 33997099, 2021). "PVT1 also decreases miR-195 expression by enhancing histone H3K27me3 and by direct sponging of miR-195 to modulate EMT in cervical cancer cells." (PMID 30679629, 2019). "In the enrolling studies, PVT1 and HOTAIR were investigated in two or more articles, and with the increased expression of the two lncRNAs, the prognosis rate was poor in cervical cancer." (PMID 28977961, 2017). "Of note, because PVT1 and MYC are frequently co-amplified in cancer, we additionally examined expression of MYC in cervical cancer and adjacent normal tissues." (PMID 27232880, 2016). "Our interest in PVT1 originated from our work and others’ demonstrating that it is a frequent site of HPV integration in cervical cancer, further suggesting an important biological function." (PMID 27232880, 2016). "Several lncRNAs, including HOTAIR, H19, mucosa-associated lymphoid tissue 1 (i.e., MALT1), growth arrest-specific 5 (i.e., GAS5), cervical carcinoma high expressed 1 (i.e., CCHE1), and Pvt1 oncogene (i.e., PVT1), are crucial in tumorigenesis, invasion, metastasis, and radio-resistance." (PMID 37081411, 2023). "In addition, MALAT1, PVT1, H19, and XIST can promote cancer cell proliferation, invasion, and migration and play a role in the progression of cervical cancer." (PMID 35262965, 2022). "Considering the present findings that miR-1286 repressed circ_PVT1-induced EMT and invasion of cervical cancer cells, we then hypothesized that miR-1286 may perform the similar phenotype caused by circ_PVT1 in C33A cells." (PMID 33109773, 2020). "Because PVT1 is predicted to interact with 5′-UTR region of RNPS1 mRNA, and is found localized in both nucleus and cytoplasm of cervical cancer cells, this may be one possible mechanism of regulating RNPS1 mRNA translation in cytoplasm." (PMID 30809433, 2019). "For instance, PVT1 forms a complex with EZH2 and then recruits EZH2 to the promoter regions of miR-195 and miR-200b, increases the trimethylation of histone H3K27, and downregulates the levels of miR-195 and miR-200b in cervical cancer." (PMID 31497532, 2019). "The current study revealed that PVT1 expression levels in cervical cancer tumors were significantly higher than in adjacent noncancerous tissue and that high PVT1 expression levels correlated with patients’ poorer overall survival." (PMID 27232880, 2016). "However, the results obtained from this study suggest that PVT1 could be involved in MMP2 and MMP9 regulation by ALKBH5 in cervical cancer cells." (PMID 37639643, 2023). "Collectively, these data suggest that co-regulation of PVT1 and MYC expression may not be as common in cervical cancer as it is in other cancer types and that the result of their interaction is unlike that described previously." (PMID 27232880, 2016).